VEZF1 (vascular endothelial zinc finger 1)
Description:
Possible transcription factor. Specifically binds to the CT/GC-rich region of the interleukin-3 promoter and mediates tax transactivation of IL-3.
Synonyms: DB1; ZNF161; CMD1OO
Tractability: PROTAC: ubiquitination databases record sites on it; its protein half-life has been measured.
Gene: Protein-coding gene on chromosome 17 (57,971,547 to 57,988,389, reverse strand). Ensembl gene ENSG00000136451.
Subcellular location: Nucleus
Subcellular location (Human Protein Atlas): Nucleoplasm
Gene Ontology:
Molecular function: DNA-binding transcription activator activity, RNA polymerase II-specific; protein binding; RNA polymerase II transcription regulatory region sequence-specific DNA binding; DNA-binding transcription factor activity, RNA polymerase II-specific
Biological process: positive regulation of endothelial cell differentiation; positive regulation of transcription by RNA polymerase II; cellular defense response; regulation of transcription by RNA polymerase II; positive regulation of DNA-templated transcription
Cellular component: nucleoplasm; nucleus
Genetic constraint (gnomAD): Loss-of-function variants: 3 observed, 44.82 expected, observed/expected ratio (o/e) 0.0669, 90% interval 0.029 to 0.17. The upper end of that interval is the gene's LOEUF score, 0.17, which puts it in group 1 of 6, group 1 being the genes least tolerant of losing a copy. Missense variants: 341 observed, 661.31 expected, observed/expected ratio (o/e) 0.52, 90% interval 0.47 to 0.56. Synonymous variants: 230 observed, 240.1 expected, observed/expected ratio (o/e) 0.96, 90% interval 0.86 to 1.07.
Gene-disease validity (ClinGen):
ClinGen rates the evidence that VEZF1 causes each of these diseases.
cardiomyopathy, dilated, 100 (autosomal dominant): No Known Disease Relationship.
Homologues: Orthologues: chimpanzee VEZF1 (99% identical), macaque VEZF1 (99% identical), rat Vezf1 (99% identical), mouse Vezf1 (98% identical), dog VEZF1 (98% identical), guinea pig VEZF1 (97% identical), pig VEZF1 (97% identical), rabbit VEZF1 (97% identical), tropical clawed frog vezf1 (80% identical), zebrafish vezf1b (58% identical), zebrafish vezf1a (57% identical). Paralogues in human: MAZ (31% identical), PATZ1 (28% identical), ZNF281 (18% identical), MTF1 (18% identical), PRDM10 (17% identical), ZNF76 (17% identical), ZNF148 (16% identical), ZNF143 (16% identical), ZNF451 (14% identical), ZNF384 (14% identical), PRDM1 (14% identical), ZNF276 (12% identical), and 24 more.
Diseases named in the same sentence as VEZF1 in open-access papers:
VEZF1 is named in the same sentence as 23 diseases in open-access papers, as found by Europe PMC text mining. Sharing a sentence is not in itself a finding about the gene and the disease. The quoted sentences say what the papers report.
ovarian carcinoma (4 papers, 2022 to 2026). A malignant neoplasm originating from the surface ovarian epithelium. "VEZF1 has been implicated in the transcriptional activation of SETBP1, thereby promoting ovarian cancer progression." (PMID 40858565, 2025). "In addition, TRIM29 can facilitate SETBP1 transcriptional activation via the vascular endothelial zinc finger 1 (VEZF1) transcription factor, promoting ovarian cancer progression." (PMID 35898891, 2022). "Vascular endothelial zinc finger 1 (VEZF1/ZNF161), a transcription factor with a C2H2‐type zinc finger motif, binds to the SETBP1 promoter region and upregulates its expression in ovarian cancer." (PMID 37489294, 2023). "Additionally, VEZF1 activates SETBP1 transcription, and the SETBP1/SET/PP2A oncogenic signaling axis promotes the malignant phenotype of ovarian cancer cells." (PMID 40858565, 2025).
dilated cardiomyopathy (2 papers, 2024). Cardiomyopathy which is characterized by dilation and contractile dysfunction of the left and right ventricles. "Additionally, mutations in Vezf1 were found to be highly associated with dilated cardiomyopathy, further establishing the role of VEZF1 in cardiomyocyte development and function." (PMID 39051183, 2024).
hepatocellular carcinoma (2 papers, 2025). A malignant tumor that arises from hepatocytes. "Global profiling of O-GlcNAcylation identified vascular endothelial zinc finger protein 1 (VEZF1) as a key substrate heavily O-GlcNAcylated in GFAT1-overexpressing hepatoma cells." (PMID 40858565, 2025). "To elucidate the role of VEZF1 O-GlcNAcylation in HCC progression, we used the CRISPR-Cas9 system to silence endogenous VEZF1 in hepatoma cells." (PMID 40858565, 2025). "Then, we investigated the O-GlcNAc modification of VEZF1 in hepatoma cells." (PMID 40858565, 2025).
liver cancer (2 papers, 2024 to 2025). An epithelial or non-epithelial malignant neoplasm that arises from the liver. "Our study provides compelling evidence that GFAT1 is not only highly expressed in HCC but also functions to enhance HBP flux and O-GlcNAcylation of the transcription factor VEZF1, thereby promoting the proliferation and migration of liver cancer cells." (PMID 40858565, 2025). "Its upregulation increases HBP flux and VEZF1 O-GlcNAcylation level, which in turn promotes the malignant progression of liver cancer." (PMID 40858565, 2025). "Subsequently, in the MHCC-97H liver cancer cell line with endogenous VEZF1 knockout, silencing TNS1 gene inhibited the promoting effect of VEZF1WT on HCC progression." (PMID 40858565, 2025). "For example, the E3 ubiquitin ligase STUB1 mediated ubiquitination can reduce the stability of VEZF1 and attenuate liver cancer progression." (PMID 40858565, 2025). "Recently VEZF1 exhibited overexpression in breast and liver cancers, suggesting a potential role in promoting cancer progression 37-39." (PMID 39479456, 2024). "In addition, our design of a potentially bioactive CPPs based on VEZF1 glycosylation site, which competitively inhibits VEZF1 O-GlcNAcylation, shows therapeutic potential in vitro and in vivo, suggesting a future therapeutic application for liver cancer." (PMID 40858565, 2025). "VEZF1 transcriptionally activates progestin and adipoQ receptor 4 (PAQR4) to accelerate HCC progression, while STUB1-mediated ubiquitination of VEZF1 leads to diminished transcriptional activity and attenuated liver cancer development." (PMID 40858565, 2025).
type 2 diabetes (2 papers, 2020 to 2022). "Specifically, upregulated miR‐483‐3p was proposed to impair the vascular injury by binding with VEZF1 in type 2 diabetes." (PMID 35833267, 2022). "It is reported that miR-483-3p could target vascular endothelial zinc finger 1 (VEZF1) to modulate endothelial integrity in patients with type 2 diabetes." (PMID 32523943, 2020).
breast carcinoma (1 paper, 2023). "ETS2 promotes telomerase expression, RARG has been linked with tamoxifen resistance in breast cancer patients, and VEZF1 is a regulator of angiogenesis." (PMID 37367050, 2023).
cervical cancer (1 paper, 2023). A primary or metastatic malignant neoplasm involving the cervix. "The intersection of LASSO and SVM-RFE analyses revealed eight hub genes in cervical cancer, which were RBBP4, SRM, GCH1, USP14, TRAIP, CBX4, VEZF1, and TOM1." (PMID 36999051, 2023).
hypertrophy (1 paper, 2021). Hypertrophy is the increase in the volume of an organ or tissue due to the enlargement of its component cells. "Additionally, differentiated spliced TFs also function in cardiac fibrosis (e.g., KLF6), angiogenesis (e.g., VEZF1), cardiac structure and contractile function (e.g., VEZF1), cardiac hypertrophy, inflammation, and regulatory T-cell homeostasis (e.g., ZFP91)." (PMID 34977163, 2021).
ischemia (1 paper, 2022). A hypoperfusion of the BLOOD through an organ or tissue caused by a PATHOLOGIC CONSTRICTION or obstruction of its BLOOD VESSELS, or an absence of BLOOD CIRCULATION. "miR-191 can inhibit the expression of Vascular Endothelial Zinc Finger 1 (VEZF1), thus inhibiting angiogenesis and promoting ischemia-reperfusion injury." (PMID 35309579, 2022).
lymph node metastasis (1 paper, 2024). "VEZF1 protein in UBC patients showed a significant positive correlation with SPOP protein expression, and significant negative correlations with the number of CD68+ and CD206+ macrophages or lymph node metastasis (N stage)." (PMID 39479456, 2024).
mesenchymal tumor (1 paper, 2025). "We report a uterine myxoid mesenchymal tumor with a novel SS18::VEZF1 gene fusion." (PMID 40878061, 2025).
osteosarcoma (1 paper, 2025). A usually aggressive malignant bone-forming mesenchymal neoplasm, predominantly affecting adolescents and young adults. "Overexpression of VEZF1 has been shown to increase osteosarcoma cell proliferation, invasion, and migration, while decreasing apoptosis." (PMID 40858565, 2025).
pneumothorax (1 paper, 2022). Abnormal presence of air in the pleural cavity. "Additionally, an identical mutation, c.A659G, in VEZF1 was found in four patients, which may be related to pneumothorax, representing a disease subtype of LAM with gentler disease severity." (PMID 36117164, 2022).
Sepsis (1 paper, 2021). Sepsis is defined as life-threatening organ dysfunction caused by a dysregulated host response to infection. "Hence, VEZF1 may be implicated in the regulation of angiogenesis in septic shock, which is one of the novel targets of anti-sepsis drug exploration." (PMID 34804111, 2021). "Not surprisingly, enhanced expression levels of significant angiogenic biomarkers including angiopoietin-2 and VEGF-A have been demonstrated in septic shock, while the role of VEZF1 in sepsis is rarely reported." (PMID 34804111, 2021).
cancer (10 papers, 2010 to 2025). A tumor composed of atypical neoplastic, often pleomorphic cells that invade other tissues. "To date, studies on the function of VEZF1 have focused mainly on cancer cells or endothelial cells, and its role in follicular development is unclear." (PMID 40973947, 2025). "Overexpressed VEZF1 in T24 cells significantly counteracted the proliferation and cancer stemness induced by U937 cells." (PMID 39479456, 2024). "VEZF1 is highly expressed in endothelial cells, and it is an important regulator for angiogenesis in cancer." (PMID 33802672, 2021). "Vezf1 is unique among endothelial factors since during development its function is restricted to vascular system thus making it an attractive target for cancer therapeutics." (PMID 29970794, 2018). "VEZF1 is a well-characterized transcription factor involved in the pathogenesis of various cancers." (PMID 40858565, 2025). "Post-translational modifications (PTMs) of VEZF1 are particularly important in cancer research." (PMID 40858565, 2025). "However, in the context of UBC, VEZF1 appears to exert a protective effect, counteracting the aggressive behavior induced by macrophages in cancer cells through the induction of SPOP." (PMID 39479456, 2024). "It remains to be determined whether VEZF1 plays a widespread role in the control of DNA methylation and what contribution this epigenetic control makes to developmental gene regulation and cancer progression." (PMID 20062523, 2010).
tumor (4 papers, 2020 to 2025). "To further ascertain the role of GFAT1-regulated VEZF1 O-GlcNAcylation in tumor growth and metastasis in vivo, we performed xenograft tumor experiments in nude mice." (PMID 40858565, 2025). "Gene ontology (GO) analysis revealed an association of many of these genes with cell adhesion, implicating VEZF1 O-GlcNAcylation in tumor development and metastasis." (PMID 40858565, 2025). "As a transcription factor belonging to the zinc finger protein family, VEZF1 is recognized for its substantial impact on tumor progression." (PMID 40858565, 2025). "Among the top 10 significantly correlated TFs with A3A RNA levels in bulk RNA-seq profiles, three TFs' (FOSL1, NFKB1 and VEZF1) expression levels were greatly different between tumor and normal tissues." (PMID 37215984, 2023).
heart disease (1 paper, 2021). "Studies have proved the role of Vezf1 in regulating the heart’s compensatory growth and the contractile function of cardiomyocytes, which may be related to human heart disease." (PMID 34138931, 2021).
VEZF1 also shares sentences with these, for which no sentence is quoted: aneurysm (1 paper); bladder cancer (1); cardiovascular diseases (1); Pneumocystis infection (1); staphylococcus aureus infection (1); systemic lupus erythematosus (1).